CD68 (CD68 molecule)
Diseases named in the same sentence as CD68 in open-access papers (continued):
Sharing a sentence is not in itself a finding about the gene and the disease.
tumor (continued). "However, the tumor cells do not express S-100 protein, desmin, or myoglobin, but do express AACT and CD68; 3) In leiomyosarcoma, the pattern of growth is predominantly fascicular, with the tumor bundles intersecting each other at wide angles." (PMID 22515616, 2012). "The scoring agreement was tested for M-CSF and CD68 expression in tumor." (PMID 22554285, 2012). "On univariate analysis, only age (P<0.05), mGPS (P⩽0.001), TNM stage (P<0.01), tumour differentiation (P<0.05), resection margin (P<0.05), LNR (P<0.001), Klintrup–Makinen score (P<0.05) and CD68+ (P<0.10) were significantly associated with cancer-specific survival." (PMID 22240784, 2012). "Reduction in tumor size correlated with a 70-80% decrease in F4/80+ and CD68+ macrophage density." (PMID 22273460, 2012). "Also, we found that high CD68 count and CD68/(CD3+CD20) ratio were associated with both MMP-11 and TIMP-2 expressions by MICs at the tumor center." (PMID 23300781, 2012). "In conclusion, we demonstrate that CD163 staining is lower than CD68, with less non-specific staining of background inflammatory cells and Hodgkin cells, therefore is a better marker for tumor associated macrophages." (PMID 22289504, 2012). "On univariate analysis, only age (P<0.05), mGPS (P<0.01), TNM stage (P⩽0.001), tumour differentiation (P⩽0.001), resection margin (P<0.10), LNR (P<0.001), Klintrup–Makinen score (P<0.05), CD8+ (P<0.05), CD68+ (P<0.10) and Ki-67 (P<0.05) were significantly associated with cancer-specific survival." (PMID 22240784, 2012). "CD11b+, CD68+ or F4/80+ TAM was largely infiltrated around lymphatic vessels of tumor mass." (PMID 21481239, 2011). "Interestingly, CD11b+/CD68+ TAM expresses higher levels of VEGF-C/D than CD11b- cells, which were also known as the main mediator of tumor-associated lymphangiogenesis and lymphatic metastasis." (PMID 21481239, 2011). "However, given the fact that CD68 staining is weak in tumor samples and that GBM stem cells show a pro-inflammatory gene expression, we believe that other cell types can, under hypoxia, also activate expression of pro-inflammatory genes." (PMID 21489226, 2011). "The tumor was positive for CD68 and vimentin in immunohistochemical staining." (PMID 22040611, 2011). "Clinically, based on this data, we could identify macrophage infiltration using CD68 staining, and then separate tumor cells for analysis of miR-223 expression." (PMID 21939504, 2011). "Estimations of the immunological balance of Gas6 and CD68 may supplement other established tumour markers, but their impact on survival will require confirmation in prospective studies." (PMID 21794149, 2011). "As we found that macrophage specific CD68 positive cells are significantly less in CR tumor than in AL tumor it is likely that pro-inflammatory cytokines release from macrophage will be less in the CR tumor tissue microenvironment." (PMID 21479220, 2011). "In addition to TNM, the expression of several proteins involved in tumour genesis, particularly Gas6, and the number of infiltrating macrophages (CD68) were analysed." (PMID 21794149, 2011). "Furthermore, CD11b+/CD68+ TAM was largely infiltrated around the tumor lymphatic vessels, and they were closely involved in the OUBC-induced lymphangiogenesis and lymphatic metastasis, possibly through secretary lymphangiogenic factors such as VEGF-C/D." (PMID 21481239, 2011). "When the M1 and M2 macrophages on the tumor sections (including the tumor islets and stroma) were counted under high-power fields, approximately 70% of macrophages were CD68+/CD163+ M2 macrophages and the remaining 30% of them were CD68+/HLA-DR+ M1 macrophages." (PMID 20338029, 2010). "In survival analysis, patients with a high stromal CD68+/FoxP3+ cell ratio (> 2.9) at the primary tumour site had a median survival of 32 months while those with a lower CD68+/FoxP3+ cell ratio (< 2.9) had a median survival of 55 months (p = 0.008) (graph not shown)." (PMID 19732435, 2009).
tumor (continued). "The histology from patients AM and IV pointed out that a subset of TAMs identified with CD68 staining were also positive for HIV p24, implying that at least some of the HIV sequences generated for this study were derived from tumor associated tissue macrophages." (PMID 19997510, 2009). "Negative hormonal receptor tumours were positively associated with lower albumin concentration (P<0.05), high Ki-67 labelling index (P<0.001) and the presence of CD68+ (P<0.05) and CD8+ (P<0.05) T lymphocytes." (PMID 18797461, 2008). "The only CD68-positive cells in the tumor were the osteoclast-like giant cells." (PMID 18081931, 2007). "Quantification of CD68 signals showed that macrophages constituted approximately half of the cells in the tumor core tissue (53.9 ± 5.6%), with the percentage slightly decreasing in the tumor edge (47.5 ± 10.0%), which is consistent with the flow cytometry analysis." (PMID 40745073, 2026). "The higher percentage of CD68 and APOE double-positive areas in the tumor core compared to the tumor edge and peritumoral normal tissue indicates that macrophages are also associated with the increased APOE in the tumor microenvironment, especially within the tumor core." (PMID 40745073, 2026). "In this study, APOE was also associated with CD68 in the tumor core but not the tumor edge." (PMID 40745073, 2026). "Low expression of IL‐11 in tumour cells was associated with significantly higher levels of leukocytes (CD45), T cells (CD3, CD4, CD8), T‐cell activation (CD44, CD25, ICOS, Tim3), dendritic cell activation, antigen presentation (CD11c, CD80, B2M, HLA‐DR) and macrophage (CD68) markers." (PMID 40673604, 2025). "Moreover, CD68/CD163 ratio was also increased in IDC-DCIS tumours (p=0.0004)." (PMID 41018083, 2025). "To validate whether recurrent AITL mutations are tumor‐specific, we performed flow sorting for 10 AITL including neoplastic‐cells (CD3+/PD1+), myeloid (CD68+/CD11B+), and B‐cells (CD3‐/CD79B+) and WES was performed on the tumor enriched cell fraction for nine AITLs." (PMID 40510016, 2025). "Abundant tumor-infiltrating histiocytes may also contribute to false-positive CD68 interpretations." (PMID 41293148, 2025). "However, high expression of ALG3 may suppress the function of CD68+CD86+ macrophages or reduce their recruitment in the tumor microenvironment, thereby weakening the anti-tumor immune response." (PMID 40475760, 2025). "The prevalence of CD68+ macrophages observed within the tumor center and periphery may explain the modest therapeutic response seen in our study; however, further histological markers should be used to distinguish between anti-tumoral and immunosuppressive phenotypes." (PMID 41514652, 2025). "This aligns with previous studies showing that the tumor microenvironment in peritumoral liver tissue differs significantly from that within the tumor and is considered prognostically relevant, characterized by factors such as CD68 + and CD206 + macrophage densities." (PMID 40595796, 2025). "These cancer-specific polarization patterns, along with CD68’s strong immune correlations, suggest tailored immunotherapy approaches - particularly combining polarization modulators (e.g., CSF-1R inhibitors) with PD-1 blockade - should be developed based on tumor-type macrophage profiles." (PMID 40918116, 2025). "Moreover, previous data from our centre revealed that a higher number of CD68 + macrophages positively correlates with tumor size, invasiveness and cancer cells proliferation, shaping macrophages as possible markers of tumor cell proliferation and, consequently, of worsened prognosis." (PMID 40415137, 2025). "Within the tumor-associated myeloid cells, CD11b+CD45hiCD68+ macrophages and CD11b+CD45loCX3CR1+ microglia exhibited higher GPNMB expression compared with that of CD11b+CD45hiCD11c+ DCs, CD11b+CD68+Ly6GloLy6Chi monocytic IMCs, and CD11b+CD68+Ly6GhiLy6Clo polymorphonuclear IMCs." (PMID 40626360, 2025).
tumor (continued). "Although this study only evaluated transfer of CD45 between T cells and TNBC cells, our FFPE data suggest that TNBC cells may also acquire CD45 from macrophages, NK cells, and other types of immune cells as evidenced by expression of immune cell markers CD14, CD56, and CD68 on tumor cells." (PMID 40183054, 2025). "CD68 is a highly glycosylated glycoprotein that is highly expressed in macrophages and other mononuclear phagocytes and used as a valuable cytochemical marker for immunostaining of monocytes/macrophages in inflammatory tissues, tumor tissues, and other immunohistopathological applications." (PMID 40836954, 2025). "Similarly, the intra-T/peri-T CSF1-R+ cell ratio was significantly lower in the CD68+ macrophage than CD20+ tumor cell compartment (0.7 ± 0.1 vs 1.2 ± 0.3, p = 4e-08) and CSF1-R+ cell count was higher in the macrophage than tumor cell compartment (252.2 ± 61.3 vs 177.6 ± 28.7, p = 8e-06)." (PMID 41415285, 2025). "To further confirm this, we performed immunohistochemical (IHC) staining for the pan-macrophage marker CD68 19, M1-like and M2b-like macrophage markers CD86 20, M2a-like macrophage marker CD206, and M2c-like macrophage marker CD163 21-23 in serial histological sections of EBV-associated tumours." (PMID 39267775, 2024). "In addition, low proportions of CD68+SHP2+ macrophages within tumor, indicated better OS." (PMID 38799432, 2024). "Furthermore, CD68 + pan-macrophages present in tumor spheroids at day 14 of culture underwent a possible myeloid lineage shift as observed by the increase in endothelial markers, which suggests a possible role of the enveloping tumor microenvironment in promoting this lineage conversion." (PMID 38254117, 2024). "We show that expression of classical macrophage-related molecules such as CD14, CD163, CD68 and several molecules involved in the function, differentiation and recruitment of macrophages in VS tissue using RT-qPCR, many of which show a correlation to VS tumour volume." (PMID 38480935, 2024). "Altogether, the associations of proinflammatory mast cells and CD68+ macrophages with better outcomes after HCC resection, along with antagonistic effect of antiinflammatory CD163+ macrophages, indicate the importance of tumor-associated inflammation as a major mechanism of antitumor immunity." (PMID 38287290, 2024). "APOC1 is primarily expressed in tumor cells and macrophages and shows a positive correlation with the expression of genes such as CD68, CD86, CD163, CXCL17, CXCL8, and IL-10, suggesting that APOC1 may promote tumor progression by influencing macrophage polarization." (PMID 39877420, 2024). "The density of CD4+ T cells (r = − 0.5187, p = 0.0001), CD8+ T cells (r = − 0.3221, p = 0.0225), CD68+ macrophages (r = − 0.4097, p = 0.0031), and PD-L1+ cells (r = − 0.4119, p = 0.003), and the number of TLSs (r = − 0.4665, p = 0.0006), were negatively correlated with tumor size." (PMID 38254190, 2024). "Interestingly, although major macrophage-specific mRNAs (CD68, CD14, and ITGAM) were relatively unchanged, the mRNAs associated with an M2 phenotype (CSFR1, CD163, MS4A4A, and CRC1) were decreased, suggesting a change toward a more M1, anti-tumor status." (PMID 38744944, 2024). "Even though its detection may support the hit-and-run hypothesis, it seems like the immune response markers analyzed in this series, such as CD8, cytotoxic T cells, PDL1 and CD68, only are increased when EBERs is expressed in more than 20% of tumor cells, defined as EBV+ DLBCL." (PMID 38280007, 2024). "Moreover, tumor cells exhibited less positive staining with CD68 and CD163." (PMID 38189834, 2024). "However, in the bulk of the untreated PDOX, while Cd68-expressing tumour-associated microglia were identified in close proximity to proliferating MKI67-positive tumour cells, Gfap-expressing astrocytes were notably absent." (PMID 37127652, 2023).
tumor (continued). "The results revealed a strong correlation between CD64+ Mφ (CD64+CD68+) density and immune-activated pathways (e.g., IFNγ response, cytotoxic cells, antigen presentation signals) and a negative association with pro-tumor signals (e.g., TGFβ, Wnt, tumor proliferation signals)." (PMID 36879284, 2023). "In addition, CD68+ TAM expression was evaluated in different sample locations (stroma vs. tumour)." (PMID 37397243, 2023). "Low tumor mesothelin expression was associated with tumor necrosis and nuclear grade 1, whereas high mesothelin expression was significantly associated with the epithelioid histotype and high density of T cells CD8+, macrophages CD68+, and collagen type I fibers." (PMID 37901248, 2023). "On the other hand, in the case of oesophageal squamous cell carcinoma, CD68+ TAMs were correlated with a favourable prognosis, suggestive that CD68+ TAMs may also function as M1 macrophages, revealing pro-inflammatory and anti-tumour effects." (PMID 37397243, 2023). "Thus, this study sought to determine the relationship between high expression of HBx and CD68+ TAMs infiltration in HBV-related HCC tumor tissues, and further evaluated the prognostic value of integrating HBx and CD68 for survival prediction in a cohort of HCC patients with chronic HBV infection." (PMID 37370037, 2023). "Similarly to patient#2, CD64+CD68-CD163- and CD64+CD68+CD163- TAM were found in the tumor nest." (PMID 37691949, 2023). "High CD47 tumor cell expression or high counts of CD68 macrophages were significantly associated with elevated levels of all TIL subsets (p < 0.02), CD163 macrophages (p < 0.001), blood vessel invasion (CD31 positive) (p < 0.01), and high tumor cell Ki67 (p < 0.004)." (PMID 36598153, 2023). "Moreover, integrating HBx and CD68 expression with clinical indicators (tumor size and micro-vascular invasion) showed the best prognostic potential with highest C-index value for survival predictivity, and this proposed model also performed better than several conventional classifications of HCC." (PMID 37370037, 2023). "Thus, we speculate that the increased infiltrating CD68+ TAMs may be M2 dominant, contributing to stimulate tumor growth activity." (PMID 35347503, 2023). "Notably, CD68+ TAMs predominantly localized to S15+ tumor cells demonstrated an adverse effect on prognosis (P = 0.026), suggesting that S15+ tumor cells might enhance the immunosuppressive role of CD68+ TAMs." (PMID 37674198, 2023). "Interestingly, our histological analyses of PDAC tissues also revealed that PD-L1 expression was predominantly located in the TME at the tumor invasion fronts along with a high proportion of macrophages (CD68+ and CD163+ cells) supporting the view that the main source of PD-L1 are stromal cells." (PMID 37449210, 2023). "However, both M1 and M2 tumor-infiltrating macrophages are generally identified by the CD68 marker." (PMID 36551522, 2022). "However, whether the elevated MDSCs and CD68+CD163+M2-like macrophages promote tumor metastasis still needs a longer follow-up visit in NSCLC patients during radiotherapy and also deserves further investigations." (PMID 35928634, 2022). "However, the signaling pathways in which CD68 is involved in tumor immunity and progression remain unclear." (PMID 35550532, 2022). "The cluster of differentiation (CD) CD68 protein is one of the most common monocytes/macrophages marker proteins, but in other mononuclear phagocyte cells and non-hematopoietic cells (mesenchymal stem cells, fibroblast, endothelial, and tumor cells) weak expression can be detected." (PMID 35740407, 2022). "The results suggested that PLIN2+CD68+TAMs may represent the tumor development degree in OSCC." (PMID 35372038, 2022). "In addition, CD68 levels were found to significantly and positively correlate with the immune score and estimate the score in all tumor types." (PMID 35550532, 2022).
tumor (continued). "Moreover, the density of CD68+CA12+ cells in tumor tissues could serve as an independent prognostic factor for both the OS and TR of HCC patients." (PMID 35362480, 2022). "Whilst there is some evidence that M2 can have tumour inhibiting activity specifically in OS lung metastasis, it appears that more detailed evaluation of sub-populations such as CD68−/CD163+ at the single cell level may be a better biological endpoint if the study were to be repeated." (PMID 35672690, 2022). "To determine whether upregulated CA12 might directly influence other functions (in addition to survival) of tumor-associated monocytes and macrophages, we analyzed the correlations between the density of CA12+CD68+ cells in tumor tissues and the clinicopathological characteristics of HCC patients." (PMID 35362480, 2022). "Although correlation among the expression of CD68, SIRPα, and PD1 was revealed, further studies evaluating the other SIRPα-expressing or PD1-expressing cells will improve the understanding of the association between its expression and the tumor microenvironment in ICCs." (PMID 35317832, 2022). "Finally, we analyzed the correlation between a series of predicted drugs and CD68 expression, which may be used for tumor immunotherapy in the future." (PMID 35550532, 2022). "In addition, VSIR was found to widely express on cancer cells, fibroblasts, macrophages, and T cells in many tumor types based on the single-cell sequencing analysis and co-express with M2 macrophage markers CD68, CD163 based on the immunofluorescence staining." (PMID 35493077, 2022). "Furthermore, the HLA-DMA and HLA-DMB genes are expressed at high relative levels, similar to those for CDH1 (epithelial cells) and CD68 (macrophages), suggesting that they may be expressed by these cell types within the tumor." (PMID 36497170, 2022). "To achieve this objective, we investigated whether AIF-1 expression in tumor tissue samples from patients with NSCLC was associated with CD68 expression (a marker of monocytes such as macrophages), IL-6 expression, VEGF expression and clinicopathological features of aggressive tumor behavior." (PMID 36520870, 2022). "Moreover, we observed the expression of CD68 in these tumor and normal controls using tissue chip." (PMID 35550532, 2022). "Thus, in the near future, multiple diagnostic assessments measuring or quantifying HIF-1α, CAIX, mTor or CD68/CD163 balance in tumor specimens and/or plasmatic samples might be proposed during the OTS patient journey to evaluate outcome risks." (PMID 35326631, 2022). "In addition, the authors found a positive correlation between CD68 and tumor size." (PMID 36139588, 2022). "However, only a few tumor cells were positive for CD68 in the present case, and we consider that further IHC and electron microscopic studies may be warranted to see the significance of CD68-IHC in FL-HCC." (PMID 34533614, 2021). "The number of CD68+ tumor associated macrophages does not correlate with the prognosis of patients with EC, while high numbers of CD163+ macrophages in the tumor stroma may be associated with both low survival, later stage, and the presence of metastases." (PMID 34203319, 2021). "Furthermore, analysis of 366 HCC tumor samples from TCGA demonstrated positive associations of tissue CRP level and genes related to myeloid cells, including CD68 and CD14, as well as chemokines and receptors for the chemotaxis of monocytes or neutrophils, such as CCL2, CCR2, and CXCL1." (PMID 35070979, 2021). "In addition, we assessed PD-L1 expression in tumor, stroma and in macrophages (CD68+)." (PMID 34906209, 2021).